MYOC (myocilin)
Diseases named in the same sentence as MYOC in open-access papers (continued):
Sharing a sentence is not in itself a finding about the gene and the disease.
glaucoma (continued). "The details of the unfolding mechanisms of WT and disease-causing myoc-OLF domains variants, particularly at physiological pH, are informative for a pharmacological chaperone therapeutic effort for myocilin glaucoma." (PMID 21283635, 2011). "We also included MYOC, OPTN, and NTE, because these genes had previously been implicated in glaucoma." (PMID 21655191, 2011). "Sequence tags from many glaucoma-related genes, including myocilin, optineurin, and WD repeat domain 36, were identified." (PMID 21528004, 2011). "In spite of the importance of myocilin in inherited glaucoma pathogenesis, little is known about its normal biological function in the TEM, especially the OLF (myoc-OLF) domain." (PMID 21283635, 2011). "Consistent with the aggregation propensity observed in mutants that lead to myocilin glaucoma, the unfolding transitions of myoc-OLF are irreversible." (PMID 21283635, 2011). "Most importantly, a glaucoma phenotype appeared to be dependent upon expression and structural conformation of some myocilin mutants in ocular tissues (see Section 2.2)." (PMID 21709622, 2011). "Variants of myocilin, localized to its olfactomedin (OLF) domain, have been linked to inherited forms of glaucoma, a disease associated with elevated intraocular pressure." (PMID 21283635, 2011). "Two of these high penetrance glaucoma genes, MYOC and OPTN, are responsible for around 4% of POAG cases overall." (PMID 21321670, 2011). "In accordance with previous experiments by different laboratories, most evidence supports the gain of function theory to explain the pathogenesis of myocilin glaucoma." (PMID 21677793, 2011). "Studies in cultured HTM cells have suggested that the UPR in response to aggregation of MYOC would represent one disease mechanism in the pathogenesis of intraocular pressure and glaucoma." (PMID 20664690, 2010). "In trabecular meshwork cells, mapracorat behaved as a partial agonist in contrast to traditional glucocorticoids, in increasing myocilin, a protein thought to be involved in steroid-induced glaucoma." (PMID 20824100, 2010). "Except for specific mutations in the MYOC and OPTN genes, details regarding the predicted clinical course associated with a glaucoma gene mutation cannot be provided." (PMID 21217896, 2010). "In the trabecular meshwork of postmortem human eyes, SPARC and another glaucoma gene MYOC responded significantly to elevated-IOP." (PMID 21042566, 2010). "To date, about 23 loci have been linked to different types of glaucoma, and four genes, myocilin (MYOC), optineurin (OPTN), cytochrome P450 1B1 (CYP1B1), and WD repeat domain 36 (WDR36), have been identified as glaucoma causing genes." (PMID 19668597, 2009). "In a previous study, the APOE -219G and -491T have been shown to affect optic nerve damage and visual field loss in glaucoma, which supports the importance of APOE expression and interaction with MYOC polymorphisms in the disease pathogenesis." (PMID 19578553, 2009). "In our pedigree study, individuals carrying both the MYOC mutation and CYP1B1 variation were affected with juvenile glaucoma with goniodysgenesis." (PMID 19668597, 2009). "Previous studies in cultured human trabecular meshwork cells have suggested that the UPR in response to aggregation of MYOC would represent one disease mechanism in the pathogenesis of intraocular pressure and glaucoma." (PMID 19148291, 2009). "Data obtained from some animal models of glaucoma support the role of extracellular mutant myocilin in the pathogenesis of glaucoma." (PMID 19023451, 2008). "Disease-associated sequence variants in three genes, myocilin (MYOC, GLC1A), optineurin (OPTN,GLC1E), and WD repeat domain 36 (WDR36, GLC1G), have been described in POAG and other types of glaucoma." (PMID 19096531, 2008). "It has been described that co-expression of wild-type/mutant myocilin reduces the secretion of the wild-type protein and that single expression of glaucoma myocilin mutants reduces its proteolytic processing." (PMID 19023451, 2008).
glaucoma (continued). "The other three families each had one individual with glaucoma with the normal Thr377Thr MYOC sequence." (PMID 18449353, 2008). "Our findings show that the Thr377Met MYOC homozygous state results in a more severe glaucoma phenotype than the heterozygous condition." (PMID 18449353, 2008). "Frequencies of myocilin inferred haplotypes in primary open-angle glaucoma, adult-onset ocular hypertension, and control subjects." (PMID 17615537, 2007). "Among the identified myocilin gene mutations, the Pro370Leu mutation (OMIM 601652; allelic variant .007) is responsible for one of the most severe glaucoma phenotypes." (PMID 17515882, 2007). "Genotype frequencies of myocilin promoter and coding sequence variations in primary open-angle glaucoma, adult-onset ocular hypertension, and control subjects." (PMID 17615537, 2007). "Besides MYOC (myocilin), at least two Mendelian glaucoma genes, TBK1 (TANK-binding kinase 1) and OPTN (optineurin), encode proteins that directly regulate PINK1–PARKIN signaling and LC3 (microtubule-associated protein 1A/1B-light chain 3) recruitment." (PMID 41516357, 2026). "Mutations in the myocilin (MYOC) gene cause elevated intraocular pressure and glaucoma." (PMID 40965407, 2025). "Hence, the knockout of MYOC emerges as a promising therapeutic approach for the treatment of MYOC-related glaucoma." (PMID 41210166, 2025). "Similarly, glaucoma onsets at an earlier age in patients with TEK mutations modified by SVEP1R997C and those with MYOC mutations modified by COL15A1R163H." (PMID 41011222, 2025). "Here, we explored whether lipoplex encapsulating Cre-mRNA can induce mutant MYOC in mouse TM and develop glaucoma in Tg-CreMYOCY437H mice." (PMID 41210166, 2025). "Furthermore, the increase in ER stress and the activation of the PERK-ATF4-CHOP mediated UPR are correlated with the pathogenesis of glaucoma in multiple MYOC-dependent open-angle glaucoma mouse models expressing S341P, P370L, and Y437H variants." (PMID 40385286, 2025). "We first evaluated whether Cre-mRNA lipoplex induces mutant MYOC selectively in the TM, leading to glaucoma in a recently developed Cre-inducible mouse model of MYOC-glaucoma." (PMID 41210166, 2025). "Interestingly, these glaucoma-related genes like MYOC, TBK1, COL1A1, COL1A2, FOXC1, LRP2, and TEK also showed significant differential expression in RCC tissues." (PMID 40808675, 2025). "Additionally, the TB-1 peptide reduced ocular hypertension in a murine glaucoma model through autophagic degradation of mutant myocilin." (PMID 39596437, 2024). "Nevertheless, studies showed that some MYOC mutations lead to glaucoma phenotypes, while certain transgenic mice expressing mutated MYOC genes do not develop glaucoma." (PMID 38212635, 2024). "Here, the relationship between unfolding and amyloid aggregation of glaucoma-associated myocilin is probed, showing that myocilin is not at equilibrium and pathogenic aggregation competes directly with unfolding." (PMID 38168102, 2024). "Hence, we reason that somatic mutations within MYOC may also contribute to glaucoma because an increase in the frequency of ultraviolet (UV) light exposure to the eye can accelerate the accumulation of disease-causing somatic mutations within the MYOC of TM cells." (PMID 38397193, 2024). "In some cases, individuals may carry dual mutations, with one in the myocilin gene and another in the CYP1B1 gene, leading to a more aggressive and earlier-onset form of glaucoma." (PMID 38435218, 2024). "Myocilin is also a protein that became known in connection with research regarding glaucoma." (PMID 38255979, 2024). "This study describes a strategy to identify rare variations that would contribute to glaucoma susceptibility in MYOC-negative families." (PMID 36833422, 2023). "Myocilin, a protein in aqueous humor that is bound to exosomes, may also contribute to the disease progression of glaucoma, since myocilin helps to clear the cell debris within the trabecular meshwork." (PMID 37047335, 2023).
glaucoma (continued). "The likelihood of pathogenicity for myocilin variants based on thermal stability can now be integrated with assessments of genetic risk for glaucoma even in the absence of clinical data." (PMID 36579626, 2023). "These experiments support the finding that genetic polymorphisms in MYOC do not confer glaucoma susceptibility, but nevertheless demonstrate that misfolding variants are present among documented population variants." (PMID 36579626, 2023). "Myocilin has been widely studied in glaucoma as a secreted protein in the trabecular meshwork." (PMID 37576554, 2023). "When CYP1B1 is mutated, the metabolic activity of E2 may be affected, leading to the upregulation of Myocilin and affecting the development of primary open-angle glaucoma (POAG)." (PMID 36704044, 2022). "Furthermore, MYOC-driven glaucoma is one of the few that occurs early in life and where variation in a single gene can have a significant effect." (PMID 36672852, 2022). "Furthermore, we construct a transgenic mouse model of N450Y myocilin mutation (Tg-MYOCN450Y) and Tg-MYOCN450Y mice exhibiting glaucoma phenotypes: IOP elevation, retinal ganglion cell loss and visual impairment." (PMID 35615698, 2022). "The role of RA signaling in the pathogenesis of POAG via myocilin transcription, or through its direct effect on retinal ganglion cells, may provide clues for new therapeutic approaches in glaucoma." (PMID 35741817, 2022). "The glaucoma gene myocilin (MYOC) has been shown to be a regulator of WNT/β-catenin pathway." (PMID 33917605, 2021). "In addition, the TMSC secretome also reversed the glaucomatous effect of dexamethasone on TM cells by reducing glaucoma markers (Myocilin and ANGPTL7) and restoring TM functional markers (CHI3L1 and AQP1)." (PMID 34572471, 2021). "Tg-MYOCY437H mice express myocilin in the TM and display early-onset glaucoma phenotypes." (PMID 33539326, 2021). "To further evaluate this issue, we decided to examine all the literature that reported on glaucoma patients with MYOC mutations and to assess the relationship between the melting temperature of mutated myocilin proteins and the age at glaucoma diagnosis of patients through a meta-analysis." (PMID 34828408, 2021). "Patients with MYOC mutations would undergo increased surveillance to detect any signs of glaucoma as early as possible, rather than the usual standard of eye care." (PMID 34828408, 2021). "In addition to these ECM and adhesion-related genes, transcriptome analysis showed that GLIS1 impacts the expression of several other TM-, IOP-, and glaucoma-related genes, including MYOC and CYP1B1." (PMID 34385434, 2021). "Indeed, compared to the wild type, the myocilin mutants responsible for glaucoma do have lower melting temperatures." (PMID 34828408, 2021). "MYOC was the first glaucoma gene identified and is responsible for approximately 4% of POAG." (PMID 32579557, 2020). "In addition, MYOC is generally considered to be closely correlated to the occurrence and development of glaucoma." (PMID 33195434, 2020). "Mutations in MYOC cause a cascade of abnormalities in the trabecular meshwork, including the intracellular retention of myocilin, reduced aqueous outflow, increased IOP, and glaucoma." (PMID 32953253, 2020). "Myocilin has also been identified as another potential genetic marker of glaucoma in AH samples." (PMID 30673862, 2019). "By contrast, our understanding of the role of myocilin in glaucoma is relatively sophisticated." (PMID 31067323, 2019). "The MYOC gene locus (known as Glaucoma 1A or GLC1A), was mapped to chromosome 1q23." (PMID 30923720, 2019). "Variations in myocilin are not a common cause of nonhereditary forms of glaucoma, as single nucleotide polymorphisms are found in both glaucoma and control populations." (PMID 31067323, 2019). "Wild-type myocilin is secreted at relatively high levels to the outflow-regulating trabecular meshwork (TM) extracellular matrix within the eye 7; the TM is diseased in most forms of glaucoma." (PMID 31067323, 2019).
glaucoma (continued). "Although NTF deprivation is not considered as the primary cause of glaucoma, evidence for a linkage between NTFs and two of the most prevalent glaucoma risk genes—myocilin and optineurin—has been found." (PMID 31484425, 2019). "However, from a protein perspective, it is easy to envision broader relevance of wild-type myocilin to glaucoma pathogenesis." (PMID 31067323, 2019). "Up to date, most myocilin research have focused on ocular tissues due to its role in glaucoma." (PMID 30557320, 2018). "To date, MYOC is the gene with mutations most strongly-linked to glaucoma and is reported in approximately one-third of all juvenile open angle glaucoma (JOAG) patients and up to 4% of all primary open angle glaucoma (POAG) cases." (PMID 30395621, 2018). "Altered myocilin secretionis alsosensitive to temperature, in support of the hypothesis that myocilin-induced glaucoma is a proteinconformational disease." (PMID 29630620, 2018). "Myocilin, a protein mainly secreted in its soluble form in trabecular cell-conditioned media and fresh eye samples, is believed to significantly influence the disease progression of glaucoma." (PMID 29738436, 2018). "In 2002, Tamm stated that it was remarkable that patients with pathological MYOC mutations were at high-risk for glaucoma, but apparently had no other disease." (PMID 30395621, 2018). "Linkage analysis led to the discovery of the myocilin gene (MYOC), which causes glaucoma." (PMID 29682502, 2018). "Furthermore, the entire mouse genome is known and easily manipulated genetically, thus allowing future studies including evaluation of the role of the MYOC glaucoma gene on DEX-OHT56." (PMID 29339763, 2018). "There is a strong genetic link between mutant MYOC and glaucoma." (PMID 30395621, 2018). "However, further validation of the interaction between FOXC1 and MYOC in animal models of glaucoma and ocular cell lines would elucidate weather the interaction is specific to HeLa cells or also occurs in tissues affected during glaucoma pathogenesis." (PMID 28575017, 2017). "Study participants without myocilin disease-causing variants and non-glaucoma controls were subjected to whole exome sequencing on an Illumina HiSeq2000." (PMID 28264060, 2017). "Myocilin, a protein involved in mendelian forms of glaucoma, may impact focal adhesion and migration of cells but the interaction among other genes with similar functions is unknown." (PMID 27623284, 2016). "Interestingly, the myocilin mutant D380A leads to the development of glaucoma, which is characterized by the progressive degeneration of the optic nerve." (PMID 25728924, 2015). "Indeed a study of 72 members of a family with MYOC-related glaucoma revealed that 96% of the family members benefited from genetic counseling and wished to know their myocilin status (9, S28)." (PMID 24665880, 2014). "It is likely that the function of myocilin is unrelated to its relationship with glaucoma etiology." (PMID 25364714, 2014). "Collectively, data indicate that myocilin is recruited to the membrane compartment, interacting with GPCR proteins during ligand-mediated endocytosis and that GPCR signaling underlies pathology in myocilin glaucoma." (PMID 24367514, 2013). "Furthermore, co-expression of wild-type and glaucoma mutant myocilin leads to both reduced myocilin secretion and processing." (PMID 23342144, 2013). "When upregulated, the wild type myocilin may lead to pathology, as is observed in cases of corticosteroid glaucoma." (PMID 23028669, 2012). "However, genes consistently implicated so far (MYOC, OPTN, WDR36) are relevant only in a limited number of families and explain a small proportion of the glaucoma cases in the general population." (PMID 22570627, 2012).
glaucoma (continued). "Myocilin is one of the candidate genes linked to POAG, the most common form of glaucoma." (PMID 23082156, 2012). "However, further in-vivo studies on animal models are necessary to provide additional supporting evidence for CYP1B1 mediated MYOC upregulation as a molecular basis for glaucoma pathogenesis." (PMID 23028769, 2012). "For example, myocilin glaucoma is frequently diagnosed between 20 and 40 years of age." (PMID 22773901, 2012). "Over expression of wild type myocilin is also believed to be involved in glaucoma pathogenesis." (PMID 23028769, 2012). "Even if the MYOC gene is expressed in several non-ocular tissues, MYOC mutants are associated to only one disease, glaucoma." (PMID 22615763, 2012). "Currently, the mechanism through which mutant MYOC protein contributes to the pathogenesis of glaucoma is unknown." (PMID 23304066, 2012). "Given the connection between myocilin and early-onset glaucoma, an understanding of the nuances of different GAG interactions with myoc-OLF may pave the way to a better comprehension of myocilin glaucoma pathogenesis." (PMID 21283635, 2011). "Adult-onset chronic open angle glaucoma, the most common type of glaucoma, has also been reported to show strong evidence for genetic heterogeneity, and at least 11 genetic loci, along with 3 genes (myocilin, optineurin, and WD repeat domain 36 gene [WDR36]), have been identified." (PMID 21921986, 2011). "Considering the low prevalence of MYOC-associated glaucoma, it is not feasible to screen whole populations for mutations." (PMID 21677793, 2011). "Four genes, trabecular meshwork inducible glucocorticoid response (MYOC/TIGR), human dioxin-inducible cytochrome P450 (CYP1B1), optineurin (OPTN), and WD repeat domain 36 (WDR36), have been identified as glaucoma-causing genes, with MYOC being the first identified POAG gene." (PMID 21655360, 2011). "The data presented here inform new testable hypotheses for interactions with specific TEM components, and will assist in design of therapeutic agents for myocilin glaucoma." (PMID 21283635, 2011). "A possible reason for the inducing of glaucoma by mutant MYOC may be the ability of the stressed ER activated the unfolded protein response (UPR) to then influence the synthesis, folding, and sorting." (PMID 20664690, 2010). "Of importance in its use for ocular indications, mapracorat increases IOP in rabbits to a lower extent than dexamethasone and increases the expression of myocilin, a protein thought to be involved in the progression of glaucoma, to a significantly lesser extent than classic steroids." (PMID 20824100, 2010). "It has been reported that glucocorticoids increase myocilin expression in trabecular meshwork cells, and that this protein may have an etiological role in steroid-induced glaucoma." (PMID 20011631, 2009). "It has been estimated that myocilin glaucoma accounts for about 3%−4% of all cases of POAG." (PMID 19287508, 2009). "This process could occur at a late age with wild-type MYOC, but might be accelerated by MYOC mutants to account for juvenile onset glaucoma." (PMID 19148291, 2009). "Recently, Park’s study had revealed that OPTN could regulate the expression of MYOC primarily through the control of mRNA stability, indicating that interaction exists between the two glaucoma genes." (PMID 19145250, 2009). "Because juvenile-onset glaucoma, which is associated with single-gene mutations, shares clinical and histopathologic features with adult-onset glaucoma, monogenic glaucoma genes like MYOC and WDR36 may be associated with complex glaucoma." (PMID 18432317, 2008). "In that sense, it has been reported that non-secretion of mouse mutant myocilin Y423H, which corresponds to human mutation Y437H, is not sufficient to cause glaucoma in MYOC-knockin transgenic mice." (PMID 19023451, 2008).